PLD1 (phospholipase D1)
Diseases named in the same sentence as PLD1 in open-access papers (continued):
Sharing a sentence is not in itself a finding about the gene and the disease.
cancer (62 papers, 2005 to 2025). A tumor composed of atypical neoplastic, often pleomorphic cells that invade other tissues. "According to The Cancer Genome Atlas, PLD1 is mutated, amplified, and/or upregulated in several types of cancers." (PMID 38945955, 2024). "PLD1-mediated cancer-initiating capacity is associated with the upregulation of β-catenin and its target genes." (PMID 38945955, 2024). "Ultimately, PLD1 inhibitor-treated cancer cells were more susceptible to cytotoxic T-cell-mediated killing." (PMID 38945955, 2024). "The expression and activity of a single nucleotide polymorphism (SNP) in the Phospholipase D1 (PLD1) gene (SNP A2698C) is significantly increased in a variety of human cancers." (PMID 37190124, 2023). "PLD1 plays a key role in PA production, and dysregulated PLD1 expression has been associated with many oncogenic signaling events and observed in various human cancers." (PMID 35007762, 2022). "As a key enzyme implicated in lipid metabolism, PLD1 was overexpression in multiple human cancers, and it was stated to be responsible for aggressive phenotypes, such as angiogenesis and chemoresistance." (PMID 28915652, 2017). "As a key enzyme implicated in lipid metabolism, PLD1 was elevated in various human cancer associating with malignant phenotypes." (PMID 27713167, 2016). "Interestingly, most of these genes are linked with cancer processes (Pld1, Fam13c, Svbp, TMem192, Zc3h7a, RTP4, Naa30, Zgrf1, Slc33a1, Dnmt3b, Map6, Plin4, Eps8L2, Alg12, Capg and Tdp2)." (PMID 37700325, 2023). "Indeed, great multi‐cancer diagnostic value in tissues was observed in small eccDNAs originated from some specific genes, especially the combination of PLD1 and ATF6, or ETV6 and ALK." (PMID 37649244, 2023). "Since upregulation of PLD1 is associated with chemoresistance in various cancer cells, we examined whether PLD1 affects resistance to TMZ chemotherapy in GSCs." (PMID 32725633, 2020). "Phospholipid metabolism-related genes, such as PLD1, have been identified to be key players in cancer stemness and chemotherapy resistance." (PMID 40951345, 2025). "PLD1 and PLD2 are implicated in cancer by activating pathways central to tumor growth, cell cycle progression and angiogenesis." (PMID 40259095, 2025). "CTNNB1 (encoding β-catenin) mutation induces TBX3 expression, which in turn inhibits phospholipase D1 (PLD1) and YAP/TAZ pathway activation, suppressing cancer proliferation and growth." (PMID 38965548, 2024). "Ultimately, PLD1 governs the self-renewal capacity of cancer-initiating cells (C-ICs) through the E2F1–miR-4496–β-catenin axis." (PMID 38945955, 2024). "PLD1 was expressed at higher levels in PDAC tissues than para-cancer tissues at the protein and RNA levels." (PMID 37381714, 2023). "PLD1 has been well-established as a key regulator of the proliferation and survival of many different cancer cells." (PMID 37381714, 2023). "In the processes of carcinogenesis and metastasis, PLD1 acts as a downstream effector of various cell‐surface receptors to trigger and regulate the propagation of intracellular signals in various cancers." (PMID 37649244, 2023). "Strikingly, the combination of small eccDNAs originated from phospholipase D1 (PLD1) and activating transcription factor 6 (ATF6) had great multi‐cancer diagnostic value." (PMID 37649244, 2023). "Due to their importance in cancer development and progression, targeting PDL1 and its signaling molecules has been suggested as a treatment strategy in different cancers with an increased PLD1 activity and expression." (PMID 37190124, 2023). "The phospholipase D1 (PLD1) enzyme reinforces a critical signaling pathway that promotes cancer progression and drug resistance." (PMID 36131027, 2022). "PLD1 can hydrolyse major membrane glycerophospholipids to the lipid second messenger PA, which plays a role in disease processes such as cancer." (PMID 35775110, 2022).
cancer (continued). "PLD1 inhibition subsequently enhanced the phagocytosis of cancer cells by macrophages through the surface expression of costimulatory molecules; as a result, the cancer cells were more susceptible to cytotoxic T-cell-mediated killing." (PMID 36131027, 2022). "PLD1 and PLD2 are overexpressed in various cancers and are intimately associated with tumorigenesis via the generation of PA13." (PMID 34471223, 2021). "We further screened for the endogenous expression level between ALDOA and PLD1 in various cancer types through the The Cancer Genome Atlas Program (TCGA) cohorts." (PMID 35127525, 2021). "This demonstrates, consistent with other studies, that the knockdown of PLD1 expression or blocking of PLD activity with specific inhibitors correlates with impaired (cancer) cell migration." (PMID 33832505, 2021). "PLD1 was reported to have an important role in sustaining cancer cell survival during metabolic stress in our previous study." (PMID 34568042, 2021). "For instance, PLD1 plays a key role in the cell transformation induced by H-Ras and is involved in the resistance of cancer cells to chemotherapeutic drugs." (PMID 32074974, 2020). "Elevated PLD1 has been reported in various malignant tumors responsible for angiogenesis, metastasis, and invasion, via multiple signal pathways." (PMID 29088790, 2017). "Of note, we showed a positive correlation between PLD1 and Sp1 expression in the cancer tissues (r = 0.357; p < 0.001)." (PMID 29088790, 2017). "For instance, prior studies indicated that PLD1 was upregulated in cancers of the intestinal and breast." (PMID 28915652, 2017). "Of note, most of the studies concluded that PLD1 overexpression was pro-tumoral, and that PLD1 was a potential therapeutic target for human cancers." (PMID 28915652, 2017). "Our data underscore the importance of recycling membrane phospholipids via autophagy to cancer cell survival during nutrient scarcity and establish PLD1 as a critical player in this important metabolic adaption pathway." (PMID 27809301, 2016). "Functionality analysis showed that elevated PLD1 had a positive correlation with angiogenesis, invasion and distant metastasis as well as chemoresistence of human cancer." (PMID 27713167, 2016). "In this paper, we report that the activity of phospholipase D1 (PLD1) is required for metabolic reprogramming of cancer cells enduring prolonged glucose deprivation." (PMID 27809301, 2016). "Here we report that phospholipase D1 (PLD1) participates in the regulation of metabolic plasticity in cancer cells." (PMID 27809301, 2016). "Further clarifying the mechanism through which PLD1 inhibition results in cancer cell death would provide a better cancer therapy." (PMID 27809301, 2016). "We then measured the effect of PLD1 inhibition on the viability of three other cancer cell lines, including MCF-7 (breast), RCC4 (renal), and HCT116 (colorectal)." (PMID 27809301, 2016). "Since both Sp1 and PLD1 contribute to the aggressive of various human cancers, we postulated that they were correlated in the disease." (PMID 27713167, 2016). "Subsequently, we knockout Sp1 expression of the cancer cells and found that PLD1 decreased concomitantly." (PMID 27713167, 2016). "In summary, our findings reveal a novel role of PLD1 in sustaining cancer cell survival during metabolic stress, and suggest PLD1 as a potential target for anticancer metabolism therapy." (PMID 27809301, 2016). "For instance, the prior studies indicated that PLD1 was upregulated in cancers of the intestinal and breast." (PMID 27713167, 2016). "As stated, PLD1 were reported to be overexpression in various human tumors and contribute to the malignant phenotypes of human cancers, such as angiogenesis, invasion and metastasis, and chemoresistence." (PMID 27713167, 2016).
cancer (continued). "In low glucose cultures, the blockade of fatty acid oxidation (FAO) by PLD1 inhibition suppresses adenosine triphosphate (ATP) production and increases reactive oxygen species (ROS), leading to cancer cell death." (PMID 27809301, 2016). "Blocking PLD1 sensitizes cancer cells to glycolysis inhibition by 2-deoxy-D-glucose (2-DG) and results in decreased autophagic flux, enlarged lysosomes, and increased lysosomal pH." (PMID 27809301, 2016). "Additionally, GeneMANIA was used to predict the gene regulatory network, revealing a complex interaction network involving several key cancer-associated genes, such as TGIF1, PLD1, and PMSC4." (PMID 40963856, 2025). "Furthermore, the canonical PLD isoforms (PLD1 and PLD2) are well known to be implicated in cancer by activating oncogenic pathways." (PMID 40259095, 2025). "Moreover, PLD1 expression is inversely correlated with ICAT levels in various cancer cells, CRC patient-derived cancer cells, and CRC tissues." (PMID 38945955, 2024). "This means that focusing on PLD1 could be a new way to treat cancers that don’t respond to existing treatments." (PMID 38945955, 2024). "Considering the highly complex interactions among cancer-relevant pathways, targeting these pathways via PLD1 inhibition may be an effective therapy for CRC patients." (PMID 38945955, 2024). "Hence, this review highlights interactions involving the PLD1 and Wnt/β-catenin signaling cascades in cancer and highlights the possibility of PLD1 as a potential target for combating cancer stemness-mediated chemoresistance." (PMID 38945955, 2024). "If PLD2 confers redundancy by generating PA in the absence of PLD1, PLD2-derived PA may mediate the regulation of cancer signaling by PLD1." (PMID 38945955, 2024). "Moreover, increased expression of PLD enzymes (PLD1 and PLD2) has been implicated as contributing factors in several types of human cancer, and the role of PLD in pathways involved in cancer progression and tumorigenesis has been reported." (PMID 36791913, 2023). "An effective PLD1 inhibitor with effects on tumor regression and immune activation in the tumor environment might offer a promising new treatment modality against cancer." (PMID 36131027, 2022). "Collectively, our findings suggest that PLD1 inhibition may function as a potential immunomodulator and offer a promising new treatment modality for cancer immunotherapy." (PMID 36131027, 2022). "As cancer stem cells contributes to drug resistance, targeting PLD1 effectively might overcome GBM‐mediated therapeutic resistance." (PMID 32869317, 2021). "In addition, phospholipase D1 (PLD1)-regulated autophagy was shown to mediate cancer cell survival under glucose deprivation through FAO induction." (PMID 30771209, 2019). "Previously, multiple studies had examined the role of PLD1 in human diseases, including cancers." (PMID 28915652, 2017). "We found that both Sp1 and PLD1 were elevated in cancer cell lines compared to HPDE." (PMID 27713167, 2016). "PLD1 is upregulated in various human cancers, including breast, uterine, and endometrial cancers." (PMID 28066718, 2016). "Since PLD1 was also reported as an oncogenic gene in various human cancers, we boldly postulated that it positive correlated with Sp1, and they could promote PDAC progression synergistically." (PMID 27713167, 2016). "Therefore, the requirement for PLD1 activity to counter glucose deprivation is common among cancer cells." (PMID 27809301, 2016). "As FA oxidation is critical to energy production and countering oxidative stress during metabolic stresses, the PLD1 inhibition-induced alteration of lysosomal functions might impair FA production needed for cancer cell survival during glucose deprivation." (PMID 27809301, 2016). "PLD1 activity is required for cancer cell survival during prolonged glucose deprivation." (PMID 27809301, 2016).
cancer (continued). "As PLD1 inhibition decreased cancer growth in low glucose medium, we reasoned that this treatment might also sensitize cancer cells to glycolysis inhibition." (PMID 27809301, 2016). "Interestingly, the expression of PLD1 protein in MDA-MB-231 cells was increased 2 days after exposure to low glucose, further supporting a critical role of PLD1 in protecting the cancer cells from glucose starvation." (PMID 27809301, 2016). "Moreover, a PLD1 inhibitor was found to sensitize cancer cells to autophagy inhibition." (PMID 38945955, 2024). "Thus, ChK-α and PLD1 may be two target enzymes involved in choline phospholipid metabolism in cancer." (PMID 38945955, 2024). "However, unlike PLD2, PLD1 has been well studied for its ability to regulate Wnt/β-catenin and its associated cancer signaling pathways in addition to affecting cancer stemness." (PMID 38945955, 2024). "Interestingly, Pld1 and Gpd1 have be reported to be critical for cancer progression and metastasis." (PMID 39512339, 2024). "Thus, autoregulation of PLD activity might be coupled to selective induction of PLD1 expression via NF-κB and contributes to cancer progression through increased matrix metalloproteinase upregulation and invasion." (PMID 38945955, 2024). "While knocking out the lipolytic PLD1 gene is not detrimental to survival across species, elevated expression is implicated in cancer, cardiovascular conditions and neuropathologies, leading to the successful development of well-tolerated mammalian PLD isoform-specific small molecule inhibitors." (PMID 36834781, 2023). "Thus, nanomedicine targeting CD44 in GBM to deliver anti‐PLD1 drugs or natural anti‐cancer molecules in combination with TMZ could offer a new therapeutic opportunity for GBM target therapy." (PMID 32725633, 2020). "Indeed, insights into PLD1 promoted more and more researchers to learn whether the inhibition of PLD1 was an alternative approach for cancer treatment." (PMID 28915652, 2017). "PLD1-dependent downstream effects are also likely to be critical for replication of cells and other viruses, since c-Myc overexpression increases accumulation of nucleotides critical for DNA replication and cell division of cancer cells and adenovirus-infected cells." (PMID 26020637, 2015). "Thus, the PH domain of PLD1 may be useful in development of effective anti- HIF-1α peptide therapeutics against cancers." (PMID 25361009, 2014). "Meanwhile, the PI3K/AKT pathway coordinates Wnt signaling through phospholipase D1 (PLD1), stabilizing β-catenin and promoting cancer stemness and chemoresistance." (PMID 41361128, 2025). "Using TIMER2.0 and GeneMANIA, we identified a complex regulatory network involving key cancer-related genes such as TGIF1, PLD1, and PMSC4, which influence the tumor’s ability to evade immune responses and metastasize." (PMID 40963856, 2025). "In our comparison between the normal and early-stage cancer groups, FKBP1A showed the highest significant p-value (p < 0.0001) among all candidate genes (PLD1, p = 0.0078, PSMA4, p = 0.0165)." (PMID 38570626, 2024). "Although the roles of PLD1 and PLD2 in cancer cells have been well studied, their functions in the tumor microenvironment have not yet been clarified." (PMID 36131027, 2022). "Additionally, PLD1/2 has been reported to regulate several growth-related signaling pathways through its lipid product PA such as the mammalian target of rapamycin (mTOR) and the Hippo pathway, highlighting their crucial roles in growth control and cancer development." (PMID 35007762, 2022). "The choline metabolism in cancer pathway (ecb05231) leads to increased levels of choline-containing precursors via the modulation of enzymes (e.g., PLA2G4A, PLD1)." (PMID 36553455, 2022). "The most important enzymes in lipid metabolism, such as Acetyl-CoA Carboxylase (ACC), Fatty Acid Synthase (FASN), ATP Citrate Lyase (ACLY), Phospholipase D1 (PLD1), Stearoyl-CoA Desaturases 1 (SCD1), are closely related to cancer metastasis." (PMID 33718168, 2021).
cancer (continued). "Collectively, these findings suggest that PLD1 plays a critical role in FA production that supports FAO in mitochondria, therefore generating energy and antioxidative stress capacity needed for cancer cell survival under glucose-deprived conditions." (PMID 27809301, 2016). "Elevation of either PLD1 or PLD2 (the two mammalian isoforms of PLD) is able to transform fibroblasts and contribute to cancer progression." (PMID 24103483, 2014). "In the present study, Wnt3a and mimicking of Wnt signaling through LiCl and BIO resulted in induction of both PLD1 and PLD2 in a variety of cancer cells." (PMID 20711340, 2010). "CARD14 expression appeared to be greater in primary cancer and reduced in bone metastasis while that of ACAS2L and PLD1 appeared to be equivalent." (PMID 16042785, 2005). "Collectively, these findings suggested that pharmacological inhibition of PLD1 enhanced the phagocytic activities of cancer cells by macrophages via modulation of ‘do not eat-me’ and ‘eat-me’ signals." (PMID 36131027, 2022). "Thus, inhibition of PLD1 suppressed FAO during glucose deprivation, depleting ATP while increasing ROS, which resulted in cancer cell death." (PMID 30771209, 2019). "Most genes from the “Pathways in cancer” (FLT3, IGF1R, DAPK2, PLD1 and MMP9) are inhibited due to the action of BE resulting in an anti-proliferative and pro-apoptotic action of the combined therapy, with the notable exception of the up-regulation of the apoptosis inhibitor BIRC3." (PMID 28359318, 2017). "Notably, PLD1 inhibition increased cell death in Atg7-depleted MDA-MB231 cells, suggesting that PLD inhibition sensitizes cancer cell to metabolic stress by the inhibition of autophagy." (PMID 26589724, 2015). "This review will introduce the classical mammalian PLD’s, PLD1 and PLD2, followed by the mechanisms of intracellular regulation and a status of the scientific literature in the crucial involvement of PLD in cancer, mostly through its role in cell migration, invasion and metastasis." (PMID 24103483, 2014). "In addition to the enzymatic activity of PLD, PLD1- or PLD2-specific binding proteins and the modulation of other regulatory factors may affect distinct cancer signaling pathways mediated by PLD isozymes." (PMID 38945955, 2024). "PLD1 inhibition reduced the expression of the “do not eat-me” signals and upregulated the levels of “eat-me” signals, subsequently enhancing the phagocytosis of cancer cells by macrophages." (PMID 36131027, 2022). "Genes such as NRAS, SPHK2, FOS, CXCR4, PLD1, GNAI2, and PLA2G4F, and their related biological process terms and pathways, such as apoptosis, MAPK signalling pathway, and cancer signalling pathways, may represent potential targets for OA treatment and diagnosis." (PMID 29968759, 2018). "Hence, these findings suggest the potential use of PLD inhibitors, especially dual inhibitor of PLD1 and PLD2, such as FIPI, may ultimately provide the most utility for cancer therapy." (PMID 28399876, 2017). "Thus, PLD1 inhibitors may function as potential immunotherapeutic agents based on ICD and immune activation and may offer a promising new treatment modality for cancer immunotherapy." (PMID 38945955, 2024). "Surprisingly, the role of PLD1 and PLD2 in prostate cancer (PCa), the commonest cancer of men in the western world, has not been widely investigated." (PMID 31673104, 2019). "Moreover, only PLD1 in the tumor microenvironment, but not PLD2, promoted tumor growth and metastasis; whereas, cell-intrinsic roles for PLD2 to accelerate cancer cells migration and invasion have been widely accepted." (PMID 28399876, 2017).